DYM (dymeclin)
Description:
Necessary for correct organization of Golgi apparatus. Involved in bone development.
Synonyms: FLJ20071; DMC; SMC
Tractability: PROTAC: ubiquitination databases record sites on it; its protein half-life has been measured.
Gene: Protein-coding gene on chromosome 18 (49,036,387 to 49,461,347, reverse strand). Ensembl gene ENSG00000141627.
Subcellular location: Cytoplasm; Golgi apparatus; Membrane
Subcellular location (Human Protein Atlas): Golgi apparatus
Gene Ontology:
Molecular function: enzyme binding; protein binding
Biological process: bone development; Golgi organization
Cellular component: cytoplasm; Golgi apparatus; membrane
Genetic constraint (gnomAD): Loss-of-function variants: 68 observed, 76.96 expected, observed/expected ratio (o/e) 0.88, 90% interval 0.73 to 1.08. The upper end of that interval is the gene's LOEUF score, 1.08, which puts it in group 4 of 6, group 1 being the genes least tolerant of losing a copy. Missense variants: 729 observed, 800.37 expected, observed/expected ratio (o/e) 0.91, 90% interval 0.86 to 0.97. Synonymous variants: 299 observed, 307.31 expected, observed/expected ratio (o/e) 0.97, 90% interval 0.88 to 1.07.
Homologues: Orthologues: macaque DYM (99% identical), pig DYM (98% identical), rabbit DYM (97% identical), chimpanzee DYM (92% identical), rat Dym (92% identical), dog DYM (91% identical), guinea pig DYM (89% identical), mouse Dym (88% identical), tropical clawed frog dym (83% identical), zebrafish dym (65% identical), Drosophila melanogaster CG8230 (42% identical), Caenorhabditis elegans C47D12.2 (37% identical).
Diseases named in the same sentence as DYM in open-access papers:
DYM is named in the same sentence as 21 diseases in open-access papers, as found by Europe PMC text mining. Sharing a sentence is not in itself a finding about the gene and the disease. The quoted sentences say what the papers report.
Dyggve-Melchior-Clausen syndrome (3 papers, 2010 to 2023). "DYM is nearly 500 kb long, and mutations in this gene cause Dyggve-Melchior-Clausen syndrome [MIM 223800], characterised by short trunk dwarfism, developmental delay, microcephaly and psychomotor retardation." (PMID 21060895, 2010). "Mutations affecting trafficking protein particle complex 2 (TRAPPC2 or Sedlin) and dymeclin, thought to have roles in protein transport between ER and Golgi, also cause nonlethal skeletal dysplasias, X-linked spondyloepiphyseal dysplasia tarda and Dyggve-Melchior-Clausen syndrome, respectively." (PMID 30439444, 2019). "SMC and DMC syndromes come under the category of autosomal recessive spondylo-epi-metaphyseal dysplasia (SEMD), which is a class of osteochondrodysplasia induced by defects in the Dymeclin (DYM) gene located at chromosome 18q21.1." (PMID 36833437, 2023).
osteochondrodysplasia (2 papers, 2023). A term referring to disorders characterized by abnormalities in the development of bones and cartilage. "Smith McCort (SMC) dysplasia is a rare, autosomal recessive, osteochondrodysplasia that can be caused by pathogenic variants in either RAB33B or DYM genes." (PMID 37359363, 2023).
Smith-McCort dysplasia (2 papers, 2017 to 2023). "Dyggve–Melchior–Clausen syndrome and Smith-McCort dysplasia are recessive spondyloepimetaphyseal dysplasias caused by loss-of-function mutations in dymeclin (DYN), the candidate gene closest to the marker at CFA7:79,570,691 associated with RCCL." (PMID 28614352, 2017). "The first genetic locus for Smith-McCort dysplasia (SMC1) was identified on chromosome 18q21 and associated with homozygous or compound heterozygous pathogenic variants in the DYM gene (encoding Dymeclin)." (PMID 37359363, 2023).
bladder cancer (1 paper, 2022). "In summary, our results demonstrated that the DYM gene not only plays an immune-related role in bladder cancer, but also promotes the proliferation, migration, metastasis and suppresses cell apoptosis of bladder cancer cells." (PMID 35769470, 2022). "K-M analysis also demonstrated that upregulated DYM was related to poor clinical outcomes in bladder cancer in TCGA database(P value <0.001), which was confirmed in GSE31684 (P value =0.021)." (PMID 35769470, 2022). "Subsequently, we confirmed that knockdown of DYM genes inhibited the cell proliferation, migration, invasion and promote apoptosis ability of bladder cancer cells." (PMID 35769470, 2022). "We further examined the biological function of DYM gene in the progression of bladder cancer." (PMID 35769470, 2022). "Therefore, the roles of DYM and MICALL2 in bladder cancer were investigated in further analyses." (PMID 35769470, 2022).
coronary artery disease (1 paper, 2025). "DYM has genetic variants previously associated with body fat percentage, and coronary artery disease." (PMID 39844050, 2025).
dyslexia (1 paper, 2010). A learning disorder characterized by an impairment in processing written words. "Along with already published biological evidence, MC5R, DYM and NEDD4L make attractive candidates for dyslexia susceptibility genes." (PMID 21060895, 2010).
gastric cancer (1 paper, 2009). A primary or metastatic malignant neoplasm involving the stomach. "The genes PLA2G4A, BMP5, MMP6, KNNMB4 and DYM were candidates for the GP202 gastric cancer cell line and the genes TXNL4B, FOXK1, PTPRJ, and SNN were candidates for the IPA220 gastric cancer cell line." (PMID 19563644, 2009).
skeletal dysplasia (4 papers, 2019 to 2025). Any Mendelian diseases that affects growth and development of the skeleton. "DYM is another medically relevant gene, where mutations are known to cause Dyggve-Melchior-Clausen syndrome (DMC), a type of skeletal dysplasia also known to be associated with brain developmental defects." (PMID 41345834, 2025).
infection (1 paper, 2018). The state of being infected such as from the introduction of a foreign agent such as serum, vaccine, antigenic substance or organism. "Transcription factors, such as ZNF503, ZNF283, DYM, and OTX1, that control genes involved in antiviral defense may affect downstream targets at later infection stages." (PMID 29997306, 2018).
DYM also shares sentences with these, for which no sentence is quoted: developmental delay (2 papers); microcephaly (2); cancer (1); celiac disease (1); intellectual disabilities (1); osteoarthritis (1); osteoporosis (1); rheumatoid arthritis (1); sarcopenia (1); spondyloepimetaphyseal dysplasia (1); tumor (1); X-linked spondyloepiphyseal dysplasia tarda (1).